CTLA4 (cytotoxic T-lymphocyte associated protein 4)
Diseases named in the same sentence as CTLA4 in open-access papers (continued):
Sharing a sentence is not in itself a finding about the gene and the disease.
autoimmune disease (continued). "Cytotoxic T-Lymphocyte Antigen 4 (CTLA-4), an immune-checkpoint receptor and regulator of T-cell activation, has become an important therapeutic target for immunotherapy in cancer and autoimmune diseases." (PMID 25349698, 2014). "On the one hand, recent data shows that CD80 favorably binds CTLA-4 and as a result, provides critical suppression of T cell responses protecting from autoimmune diseases." (PMID 25505551, 2014). "The true molecular nature of the material in these sera recognized by anti–CTLA-4 Abs has been questioned by the same laboratory that originally reported the increase of sCTLA-4 in autoimmune disease." (PMID 24928993, 2014). "Major progress has been made in designing new therapies for autoimmune diseases with the use of CTLA-4-related biological agents." (PMID 25229821, 2014). "PD-1 and CTLA-4 signals result in Treg induction and maintenance, and subsequent outbreak of autoimmune diseases." (PMID 25105508, 2014). "Based on its role in the regulation of the activation of T cells and T cell and B cell interactions, CTLA4 has been considered to be a permissive candidate gene involved in the etiology of autoimmune diseases." (PMID 24465825, 2014). "CTLA-4-Ig (Abatacept) treatment is used in RA and has been extensively evaluated in different autoimmune disorders and new clinical trials are being conducted in T1D patients." (PMID 25229821, 2014). "In preclinical models, anti-CTLA-4 treatment is known to enhance onset and severity of several T cell-mediated experimental autoimmune diseases, including murine models of encephalomyelitis, myasthenia gravis, and type 1 diabetes." (PMID 25349698, 2014). "It has been reported that +49 A/G polymorphism in CTLA4 gene alters the intracellular distribution of CTLA-4, IL-2 production, and T-cell proliferation, suggesting their possible role in autoimmune diseases." (PMID 23970995, 2013). "The CTLA4 molecule is expressed on activated T lymphocytes and has recently been identified as an important negative regulator in autoimmune diseases." (PMID 22536280, 2012). "CTLA4-Ig has shown therapeutic efficacy in several autoimmune diseases including rheumatoid arthritis, and in experimental models of autoimmune diseases." (PMID 22536543, 2012). "Based on the encouraging results in murine models, the efficacy of CTLA-4 Ig has been examined in patients with autoimmune diseases." (PMID 22997525, 2012). "Particularly, administration of CTLA-4 Ig has shown great promise in animal models of autoimmune diseases and has been gaining increasing attention in clinical investigation in several autoimmune diseases in humans." (PMID 22997525, 2012). "As for treatment of autoimmune disease models, CTLA-4 Ig treatment prevents autoantibody production, reduces the severity of lupus nephritis, and prolongs survival in NZB/NZW F1 mice." (PMID 22997525, 2012). "In some conditions, the administration of decoy coinhibitory receptors (e.g., CTLA-4 Ig) or mAb against coinhibitory molecules suppresses the responses of self-reactive T cells in autoimmune diseases." (PMID 22997525, 2012). "Apart from polymorphisms within the major histocompatibility complex (MHC) and CTLA-4, a 1858 T>C polymorphism of PTPN22 gene is currently a recognized risk factor for autoimmune diseases." (PMID 23072316, 2012). "Cytotoxic T lymphocyte-associated antigen 4 (CTLA4, ENSG00000163599) has demonstrated genetic linkage to a number of autoimmune diseases, including MS, and involves genetic regulation of alternative splice forms." (PMID 20856809, 2010). "For example, a number of autoimmune diseases have been associated with variants in the PTPN22, TNFAIP3 and CTLA4 genes." (PMID 20854658, 2010). "For example, injection of anti-CD25 antibodies alone or in combination with anti-CTLA-4 antibodies into normal animals is known to induce localized autoimmune disease." (PMID 20011659, 2009).
autoimmune disease (continued). "The relation between sCTLA-4 and disease activity in different autoimmune diseases argues for a blockade of the inhibitory signal resulting from CTLA-4/CD80-CD86 binding." (PMID 19570209, 2009). "A soluble form of CTLA-4 (sCTLA-4), resulting from an alternative splicing, has been identified and was found increased in several autoimmune diseases." (PMID 19570209, 2009). "CTLA-4 blockade enhances T cell responses in vitro and in vivo, augments antitumor immunity and exacerbates autoimmune diseases." (PMID 16259622, 2005). "The CTLA-4 gene has been found to play a critical role in the pathogenesis of autoimmune diseases such as GD, HT and T1D." (PMID 15762980, 2005). "Our research, along with that of others in the field, demonstrates that TIGIT, similar to PD-1 and CTLA-4, could be another critically important molecule in effectively managing autoimmune diseases." (PMID 41597269, 2026). "One study also found links between the CTLA4 gene SNPs and autoimmune disorders." (PMID 39854591, 2025). "The second hypothesis is supported by recent genetic studies, which have identified shared susceptibility loci, such as CTLA4, PTPN22, and TNFAIP3, across multiple autoimmune diseases." (PMID 40725836, 2025). "CTLA4 gene SNPs have been studied in relation to cancer in addition to autoimmune diseases." (PMID 39854591, 2025). "Similarly, the diseases with prominent autoimmune disorders such as LRBA and CTLA-4 deficiencies are determined as IPEX-like diseases and, owing to their convergent manifestations and dysfunctions, as well as altered numbers of Tregs." (PMID 40804844, 2025). "Although CTLA-4 is highly expressed in Tregs and serves a crucial role in conventional T cell self-tolerance, CTLA-4 blockade combined with Treg depletion strategies has demonstrated significant therapeutic efficacy in tumor treatment and autoimmune disease management." (PMID 40463500, 2025). "The proband and an affected sister showed a G/G genotype for CT60, associated with a low expression of a soluble isoform of CTLA-4 lacking the third exon and a predisposition to autoimmune diseases, whereas the father was heterozygous A/G." (PMID 40149457, 2025). "Blocking its function may enhance the antitumor response, similar to that of PD-1 or CTLA-4 inhibitors, while activating it may be applied in treatment of autoimmune diseases, transplantation, and sepsis." (PMID 40574024, 2025). "In autoimmune diseases or organ transplantation, costimulatory inhibition using monoclonal antibodies, soluble versions of the high-affinity receptors CD80 and CD86, and cytotoxic T-lymphocyte-associated protein 4 (CTLA-4) promotes tolerance in animal models." (PMID 39062908, 2024). "Additionally, downregulation of CTLA-4 expression plays a catalytic role in various autoimmune diseases, including IBD." (PMID 38313367, 2024). "Therefore, it seems essential that practicing pediatricians should take into account the possibility of CTLA-4 insufficiency in the differential diagnosis of autoimmune diseases." (PMID 39624103, 2024). "The expression of CTLA-4 in activated T cells and Treg cells has been reported to play a crucial role in the regulation of the therapeutic efficacy of ICIs in the treatment of autoimmune diseases and cancer." (PMID 39795946, 2024). "Furthermore, CTLA-4 knockout mice develop a dysregulated T-cell immune response, resulting in autoimmune disease and severe lupus-like syndrome." (PMID 38399467, 2024). "In autoimmune diseases, silencing immune system activation could be achieved by stimulating silencers, for example, CTLA-4." (PMID 38279272, 2024). "CCR5 and CTLA4 are both key regulators of the immune response and, although they act in different ways and at different stages of the immune response, play an important role in autoimmune diseases, such as MS." (PMID 39000519, 2024).
autoimmune disease (continued). "Lipopolysaccharide‐responsive and beige‐like anchor protein (LRBA) controls intracellular trafficking of Cytotoxic T‐lymphocyte protein 4 (CTLA‐4), and a loss of LRBA causes the insufficient CTLA‐4 expression on the surface of Tregs, resulting the development of autoimmune diseases." (PMID 40625455, 2024). "The study illustrated that deletion of CTLA-4 in adult mice leads to autoimmune disease." (PMID 37497212, 2023). "Research has demonstrated that CTLA-4 is a critical negative regulator of autoimmune diseases." (PMID 37497212, 2023). "Theoretically, the decreased expression of CTLA4 contributes to autoimmune disease." (PMID 37760867, 2023). "CTLA-4 is a co-inhibitory surface molecule that is constitutively expressed in Treg and its expression assay is of great interest for the diagnosis and clinical management of both PIRDs and autoimmune diseases (rheumatic diseases)." (PMID 38077340, 2023). "While engagements of CTLA-4 and PD-1 to their respective ligands deactivate effector T cells, they enhance Treg function, as supported by the observation that blockade of CTLA-4 and PD-1 are known to exacerbate autoimmune diseases through deactivation of Tregs." (PMID 37965256, 2023). "Furthermore, certain germline CTLA4 and PDCD1 (encoding for PD-1 protein) gene polymorphisms have been associated with both the development of autoimmune diseases and susceptibility to ICI-induced endocrine irAEs." (PMID 36900420, 2023). "Expression status of CTLA-4 in different autoimmune diseases." (PMID 37497212, 2023). "The CTLA4 locus has been involved in the regulation of several autoimmune diseases in humans." (PMID 37342323, 2023). "Furthermore, a soluble form of CTLA-4 is present in patients with various autoimmune diseases, such as autoimmune thyroid diseases, myasthenia gravis, and systemic lupus erythematosus (SLE)." (PMID 37342323, 2023). "In humans, CTLA-4 deficiency caused by autosomal heterozygous mutation of the CTLA-4 gene or mutations in recycling partner LPS-Responsive beige-like anchor (LRBA) protein are associated with severe autoimmune diseases." (PMID 38127423, 2023). "Additionally, several studies have shown that CTLA-4 variants affect CTLA-4 expression on the cell surface, which was associated with autoimmune diseases, such as Grave’s disease, Hashimoto’s thyroiditis and atopic dermatitis." (PMID 37107632, 2023). "Role of anti-CTLA-4/CTLA-4Ig in different autoimmune diseases." (PMID 37497212, 2023). "For example, the CTLA4 (T-lymphocyte antigen 4) +49A/G (rs231775) and CT60 (rs3087243) gene variants have been associated with a predisposition for autoimmune diseases in different populations; however, their involvement in the development of vitiligo remains controversial." (PMID 36163113, 2022). "It is worth mentioning that the immune regulatory function of co-inhibitory receptors such as CTLA-4, PD-1, LAG-3, TIM-3, and TIGIT was initially identified in autoimmune disorder models, since their blockade or deficiency led to the induction or exacerbation of the disease." (PMID 35893056, 2022). "Germline CTLA4 and PDCD1 gene polymorphisms are associated with autoimmune diseases." (PMID 35912205, 2022). "Although no disease equivalent is known in humans, the importance of CTLA-4 in keeping tolerance is supported by fact that polymorphisms in the gene are associated with an increased risk of autoimmune disease." (PMID 35784333, 2022). "Furthermore, we identified clinically relevant mutations that cause autoimmune disease, which selectively disrupted CD86 transendocytosis, by affecting either CTLA-4 recycling or CD86 binding." (PMID 35999394, 2022). "Both CTLA-4 and PD-1 are also involved in development of autoimmune disorders." (PMID 36204105, 2022).
autoimmune disease (continued). "Interestingly, it has been reported for several autoimmune diseases that costimulation blockade of the CTLA-4 axis selectively decreases the proportion of T follicular helper cells, thereby reducing T cell help for germinal center B cells." (PMID 33515310, 2021). "However, the roles of various CTLA4 isoforms in autoimmune disease mechanisms remain to be clarified and additional studies are required to explore these signaling pathways." (PMID 34484216, 2021). "Dysregulated expression of CTLA-4 leads to immune homeostasis imbalance and autoimmune diseases." (PMID 34054801, 2021). "As a result, this leads to inhibition of CTLA4 and PD-1 pathways, which were considered the most important immunoregulatory pathways that configure immune responses in a variety of immunological disorders including cancers and autoimmune diseases." (PMID 37305162, 2021). "In addition to loci implicated in lymphocyte function and development shared with other autoimmune diseases such as HLA, BACH2, PTPN22 and CTLA4, we associate two protein-coding alterations in Autoimmune Regulator (AIRE) with AAD." (PMID 33574239, 2021). "In both mice and patients treated with CTLA-4 inhibitor, there are decreased circulating Treg and increased T helper (Th) 17 cells, whose enhancement is known to be involved in the pathogenesis of autoimmune diseases." (PMID 34898551, 2021). "Indeed, many single-gene traits linked to autoimmune diseases (e.g., AIRE and CTLA-4) play important roles in the production or function of Treg cells." (PMID 33923792, 2021). "CTLA-4 blockade has also been shown to increase in circulating type 17 T helper cells (TH17), which produce IL-17, a proinflammatory cytokine implicated in many autoimmune diseases." (PMID 34201529, 2021). "Animal models with the knockout of CTLA-4 are important for the study of autoimmune diseases." (PMID 34201650, 2021). "Conversely, Tregs lacking CTLA-4 were found to cause a fatal autoimmune disease with similar characteristics to mice lacking CTLA-4, albeit with some degree of delayed kinetics." (PMID 34125407, 2021). "Abatacept (Bristol-Myers Squibb, Orencia ®) and Belatacept (Bristol-Myers Squibb, NULOJIX®) are two FDA approved biologics, consisting of the extracellular domain of CTLA-4 fused to the Fc domain from human Ig, used to treat autoimmune diseases and kidney transplant rejection, respectively." (PMID 32497097, 2020). "CTLA-4 is a surface receptor on T cells, which functions to downregulate T cell activity and polymorphism of CTLA-4 has been shown to be associated with certain autoimmune diseases." (PMID 32153545, 2020). "Indeed, CTLA-4 knockout mice develop lymphoproliferative disorders including multiorgan infiltration, tissue damage, and autoimmune diseases which ultimately leads to their death less than a month after birth." (PMID 32117295, 2020). "The identified genes include cytotoxic T lymphocyte antigen-4 (CTLA-4), which might also be associated with T1DM and many autoimmune diseases such as Graves’ disease, and autoimmune hypothyroidism." (PMID 33272321, 2020). "Current publications showed association between autoimmune diseases and chromosome 10p15 region for IL2RA (interleukin 2 receptor-α), chromosome 2q33 region for CTLA-4 (cytotoxic T-lymphocyte antigen-4) and chromosome 2q24 region for IFIH1 (interferon induced with helicase C domain 1)." (PMID 32974248, 2020). "As we know, there is no data suggesting the association between CTLA-4 and IVIg therapy in autoimmune diseases." (PMID 32148437, 2020). "The immune regulatory function of co-inhibitory receptors, including CTLA-4, PD-1, TIM-3, TIGIT, and LAG-3, was first discovered in the setting of autoimmune disease models, in which their blockade or deficiency resulted in induction or exacerbation of the disease." (PMID 31974523, 2020).
autoimmune disease (continued). "Immune regulation by CTLA-4 is important since CTLA-4 knockout mice develop fatal lymphoproliferative disorders and mutations in the CTLA-4 gene have been associated in humans with an increased risk of autoimmune disease." (PMID 30759880, 2019). "Importantly, the essential role of CTLA-4 in autoimmune regulation was further highlighted by the fact that blockade of CTLA-4 signaling in multiple animal models resulted in aggravation of autoimmune diseases." (PMID 31214024, 2019). "CTLA-4-knockout mice often develop autoimmune diseases, such as pancreatitis and myocarditis." (PMID 31412566, 2019). "The central role of CTLA4 for keeping T cell activation in check was highlighted from studies with genetically modified mice that are deficient for CTLA-4, which are characterized by profound immune dysregulation and autoimmune disease." (PMID 31340499, 2019). "Given links between CTLA-4 gene polymorphisms (in particular CTLA-4 59A > G variant) and incidence of autoimmune diseases, it is possible that CTLA-4 gene polymorphisms may mediate a certain fraction of irAEs related to CTLA-4 inhibition." (PMID 30170622, 2018). "Indeed, biologics designed around CTLA-4, such as CTLA-4 fused to FcR (brand name Belatacept) have been used successfully to treat a variety of autoimmune diseases and in organ transplantation, and show some efficacy in T1DM animal models and clinical trials." (PMID 29963051, 2018). "Interestingly, CTLA4-Ig (abatacept) is currently under investigation as a first-line biologic for the treatment of autoimmune diseases, such as RA." (PMID 29867939, 2018). "This may indicate that in humans, on one hand, a subset of Treg cells that express CTLA‐4 is required to prevent a defined spectrum of autoimmune diseases that are seen in patients with CTLA‐4 haploinsufficiency." (PMID 29484183, 2018). "Although the autoimmune diseases against self-antigens were much milder and at later onset in PD-1/PD-L1/L2 deficient mice than in CTLA-4−/− mice, anti-PD-1 mAbs exhibited stronger antitumor effects than anti-CTLA-4 mAbs in tumor models." (PMID 29255458, 2017). "CTLA-4 plays an important role in the development of a variety of autoimmune diseases." (PMID 28133421, 2017). "Recombinant sCTLA4 inhibits T-cell proliferation in vitro, indicating that a reduction in the levels of this form of CTLA4 could lead to inefficient blocking of the immune response, triggering an autoimmune disorder." (PMID 29299173, 2017). "Furthermore, CTLA-4 polymorphisms -318 C > T, +49 A > G, and CT60 A > G are associated with susceptibility to autoimmune disorders." (PMID 26108796, 2015). "The CTLA4 knockout mouse exhibits a profound spontaneous autoimmune disease." (PMID 25003519, 2014). "High concentrations of soluble CTLA-4 can be detected in patients with various autoimmune diseases." (PMID 25538704, 2014). "A role for CTLA-4 in autoimmune diseases is suggested by the observation that blockade of B7/CTLA-4 interaction via administration of anti-CTLA-4 mAb exacerbates autoimmune diseases in animal models such as experimental autoimmune encephalomyelitis and type 1 diabetes (T1D)." (PMID 24605322, 2014). "Many of the non-HLA genes, such as PTPN22 and CTLA-4, have been previously studied in MG and other autoimmune diseases and their association with MG has been reevaluated in more cohesive groups of patients." (PMID 24294607, 2013). "However, despite the large number of studies of CTLA-4 SNPs in autoimmune diseases, so far there is still little published data regarding human cancers." (PMID 23936819, 2013). "Single nucleotide polymorphisms (SNPs) in the CTLA4 and microsatellite polymorphism in FOXP3 gene region were also reported to be associated with several autoimmune diseases including, type-1 diabetes, systemic lupus erythematosus, autoimmune thyroid diseases and celiac disease." (PMID 22911710, 2012).